IL1B (interleukin 1 beta)
Diseases named in the same sentence as IL1B in open-access papers (continued):
Sharing a sentence is not in itself a finding about the gene and the disease.
osteoarthritis (continued). "Our data show that FJH-KO supplementation in rats with MIA-induced osteoarthritis significantly decreased the serum levels of PGE2, IL-1β, and TNF-α compared with those in rats without FJH-KO supplementation." (PMID 33233504, 2020). "Primary FLS from patients with RA or osteoarthritis were stimulated with the mitogen platelet-derived growth factor (PDGF) and the cytokine interleukin-1β (IL-1β) in the presence or absence of MTX." (PMID 29554943, 2018). "Moreover, the treatment with osteotropic factors, such as vitamin D3, IL‐1β, TNF‐α, PGE2, IL‐6, but not PTH, and IL‐17, has been correlated with an increased membranous localization of RANKL on low osteoarthritis osteoblasts compared with high osteoarthritis osteoblasts." (PMID 28425564, 2017).
breast cancer (573 papers, 2004 to 2026). A primary or metastatic malignant neoplasm involving the breast. "This study is cited here as a pre-2015 mechanistic/landmark study (not included in the meta-analysis), providing early evidence that IL-1β expression is associated with bone tropism in breast cancer." (PMID 41007766, 2025). "Correlation analysis between plasma cytokine levels and clinicopathological features revealed that elevated levels of IFN-γ, IL-1β, IL-2, IL-6, and IL-12 (p40) were significantly associated with advanced clinical stages of breast cancer (P < 0.05)." (PMID 40612845, 2025). "This showed that the role of modifying factors and the illness phenotype must be taken into consideration when addressing the connection between IL-1β polymorphic variations and breast cancer risk." (PMID 40584290, 2025). "Consistently, a different study established the role of inflammasome activation in tumor-associated macrophages (TAMs) and consequent IL-1β production, which generated an inflammatory microenvironment promoting breast cancer progression." (PMID 39858071, 2025). "A LASSO Cox regression model incorporating PRMT1, PARP1, P65, and IL-1B indicates that these molecules are linked to poor prognosis in breast cancer, confirmed by the GSE6532 dataset." (PMID 40927753, 2025). "The research of biomarkers associated with bone metastasis in breast cancer examines IL-1β expression, NR2F1, and others as possible indicators of bone metastasis or dormant disseminated tumor cell state." (PMID 41465319, 2025). "It has been confirmed in breast cancer that IL-1β can promote tumor progression by recruiting tumor-associated macrophages, while blocking IL-1β can inhibit tumor immune escape." (PMID 39003253, 2024). "IL-10 downregulates the expression of Th1-type cytokines and increases the immune tolerance of cancer in the tumor microenvironment, while IL-1β is associated with an increased risk for bone metastasis in human breast cancer." (PMID 38397942, 2024). "The role of IL-1β and Wnt signaling has also been implicated in the bone metastatic growth of breast cancer, which will be discussed in the section dedicated to the IL-1 family in bone metastasis." (PMID 38334625, 2024). "Others have reported that the secretion of IL-1β by tumor-infiltrating myeloid cells was associated with more advanced disease in primary breast cancer." (PMID 39224600, 2024). "Increased levels of the pro-inflammatory cytokine IL-1β in the tumor microenvironment and serum have been associated with tumor growth, progression, angiogenesis, and recurrence in breast cancer." (PMID 38990306, 2024). "IL-1β in primary tumors is reportedly a promising biomarker for predicting the increased risk of bone metastasis in breast cancer patients." (PMID 37090158, 2023). "Through searching for the NCBI GEO dataset, the expression of NLRP3, PYCARD, CASP1, and IL-1β genes in the tumor-associated stroma of breast cancer patients were found to be increased with the pathological stage when compared with normal breast stroma." (PMID 38031068, 2023). "Western blot analysis demonstrated that knockdown of ZNF‐148 increased the expression levels of pyroptosis‐associated biomarkers (NLRP3, ASC, IL‐1β, and IL‐18) in breast cancer cells, which was reversed by cotreating cells with NAC and ALA." (PMID 37909239, 2023). "In agreement with our in vivo outcomes, high levels of IL1-β were linked to breast cancer aggressiveness and poor prognosis." (PMID 37340387, 2023). "Activation of macrophage GPBAR1 causes Interleukin 1 Beta (IL1B) release, and macrophage-derived IL1B causes breast cancer cells to release CCL13." (PMID 36834607, 2023). "For cancer cell-derived inflammasomes, NLRP3 inflammasomes and downstream IL-1β secretion can be activated by breast cancer susceptibility gene 1 (BRCA1) deficiency through ROS production leading to promoted metastasis in breast cancer cells." (PMID 36932407, 2023).
breast cancer (continued). "IL-1β has been linked with poor prognosis in breast cancer and plays a critical role in the recruitment and maturation of adaptive T cell-mediated immunity including CD4+ and CD8+ T cells and myeloid cells." (PMID 36835413, 2023). "High expression of IL-1β in the primary tumor is associated with disease recurrence at any site for breast cancer, and specifically with bony metastases." (PMID 37065483, 2023). "Both in vitro and in vivo studies have demonstrated an association between IL-1β expression and metastatic potential for breast cancer." (PMID 37065483, 2023). "Both pyroptosis-related inflammasomes including NLRP1, NLRP3, NLRC4, AIM2, and the following inflammatory cytokines IL-1β and IL-18 are associated with the immune system in breast cancer." (PMID 36119049, 2022). "Kaplanov found that implanted breast cancer tumors regressed in IL-1β-deficient mice or in wild-type mice treated with anti-IL-1β antibodies." (PMID 35912252, 2022). "And in both murine and human breast cancer models, tumor progression was associated with elevated levels of IL-1β at primary and metastatic sites." (PMID 36276078, 2022). "Cancer-associated fibroblast–derived NLRP3 inflammasome and IL-1β facilitated tumor growth and metastasis by modulating the tumor microenvironment towards an immune suppressive milieu in breast cancer." (PMID 35739593, 2022). "The levels of MDSC in mice harboring mammary carcinoma were positive association with IL-1β expression levels." (PMID 35739593, 2022). "This elevated expression of IL-1β is more likely to be associated with establishment of inflammatory tumor microenvironment and breast cancer progression." (PMID 33686176, 2021). "The study suggests that IL-1β stimulates the VM and its associated events in breast cancer cells via p38/MAPK and PI3K/Akt signaling pathways." (PMID 34055597, 2021). "Cytokines such as IL-1β and tumor necrosis factor α have also been linked to the risk and prognosis of breast cancer." (PMID 33962395, 2021). "VM-associated responses induced by IL-1β in breast cancer cells was mediated via p38/MAPK and PI3K/Akt signaling pathways." (PMID 34055597, 2021). "Accumulating evidence has demonstrated that elevated expression and polymorphisms of IL1B acted as a crucial risk factor in various cancers, involving cervical cancer, breast cancer, non-small cell lung cancer." (PMID 33995379, 2021). "IL-1β is also linked to the migration and invasion in breast cancer, for example through loss of E-cadherin and an increase in MMP-2 and MMP-9, leading to a degradation of the extracellular matrix." (PMID 34944905, 2021). "In silico meta-analysis of the expression of the genes CASP1, NLRP3 and IL-1β in breast cancer exhibited an association with prolonged overall survival." (PMID 33840390, 2021). "In another study, Il-1β-deficient mice exhibited profound regression of primary tumor growth in a syngeneic orthotopic breast cancer mouse model." (PMID 33686176, 2021). "Breast cancer cell membrane-associated transforming growth factor-beta (TGF-β) is required for IL-1β production by DCs." (PMID 34602858, 2021). "Consistently, the drug‐activated autophagy was proven to reduce the secretion of IL‐6 in chondrocytes, while the suppression of autophagy by deleting Atg7 caused increased export of IL‐1β, IL‐6 and IL‐8 in adipocytes and breast cancer cells." (PMID 33963627, 2021). "It has been observed that implanted breast cancer tumours regress in mice deficient in IL-1β or in wild-type mice treated with anti–IL-1β antibodies." (PMID 33658555, 2021). "This, in turn, promoted IL-1β secretion from tumor-associated macrophage, leading to systemic inflammation for breast cancer metastasis." (PMID 33686176, 2021). "Studies propose an association between increased IL-1β expression, breast cancer metastasis, and bone microvasculature." (PMID 34055597, 2021).
breast cancer (continued). "IL-1β is implicated in murine breast cancer development and metastasis, namely by favoring inflammatory immune cell infiltration in the tumor bed and CD8+ T cell inhibition." (PMID 33261061, 2020). "Increased IL-1β levels in tumors and serum are associated with increased tumor grade and enhanced invasion in several cancers, including breast cancer, and are correlated with poor prognosis." (PMID 32397236, 2020). "For instance, in the MMTV-NeuV664E BALB/c model, the invasive conversion of the mammary tumors was associated with an upregulation of the IL-1β transcriptional signature." (PMID 33042810, 2020). "Inactivation of NLRP3 inflammasome driven by miR-233-3p has been found to decrease the expression of NLRP3 inflammasome-associated proteins, ASC, IL-1β, and IL-18 in breast cancers and suppress tumor growth." (PMID 33613533, 2020). "Signaling through GPER-1 has been shown to trigger the expression of IL-1β and IL-1R1 in cancer-associated fibroblasts and breast cancer cells, respectively." (PMID 33117280, 2020). "Several studies have found that the DHA can trigger caspase-1 and GSDMD activation to cause pyroptosis in breast cancer cells, and enhance the secretion of IL-1β." (PMID 32182796, 2020). "Altogether, our study highlights a new role for the inflammasome in promoting invasive breast cancer progression by facilitating tumor infiltration with neutrophils, while impeding the NK cell-associated anti-tumoral response independently of IL-1β and IL-18." (PMID 33042810, 2020). "IL-1β expression in primary tumors is a potential biomarker for predicting breast cancer patients who are at increased risk of developing bone metastasis." (PMID 33339340, 2020). "With respect to breast cancer, the presence of IL-1β within the tumor microenvironment is frequently associated with poor prognosis, suggesting a pro-tumoral role for this cytokine." (PMID 33042810, 2020). "In breast cancer, IL-1β production is associated with higher rate of recurrence and is critical for tumor proliferation, angiogenesis, migration, and invasion." (PMID 31685946, 2020). "Breast cancer-associated fibroblast (CAF)-derived IL-1β in TME drives an immunosuppressive phenotype by promoting TAM’s reprogramming to an M2-like phenotype and restricting the accumulation of T cells in tumors." (PMID 33613533, 2020). "TNFα, IL-6, and IL-1β are all elevated in obese breast cancer patients and are associated with breast cancer progression and outcomes." (PMID 32630445, 2020). "In this study, production of IL-1β in primary breast cancer tumors was linked with advanced disease." (PMID 31231372, 2019). "Taken together, these findings demonstrate a tumour-promoting role for CAF-derived NLRP3/IL-1β, associated with alterations of immune cell infiltration into mammary tumours." (PMID 31558756, 2019). "Recent studies have implicated interleukin IL-1β in the systemic upregulation of G-CSF in mouse models of breast cancer." (PMID 31552036, 2019). "A recent report showed that IL-1β orchestrates tumor-promoting inflammation in patients with high-risk HER2-negative breast cancer who would benefit from IL-1-blocking therapeutics with anakinra (described later on)." (PMID 31182982, 2019). "Activated inflammasome and increased IL-1β production in tumor-associated macrophages generated an inflammatory microenvironment that promoted tumor growth and metastasis in animal and human breast cancer models." (PMID 30634494, 2019). "In human breast cancer, higher expression of IL-1β is associated with tumor invasiveness and aggressive tumor biology." (PMID 31182982, 2019). "Among these, polymorphisms in TNFa, IL6, and IL1-b were associated with fatigue after breast cancer treatment completion." (PMID 31795208, 2019).
breast cancer (continued). "Numerous reviews have also reported the strong association between interleukins and breast cancers, notably IL1β, IL6, and IL8." (PMID 31398937, 2019). "In previous work, we demonstrated that the inflammatory cytokine interleukin 1β (IL-1β)-induced upregulation of genes was associated with chemoresistance in breast cancer cells." (PMID 30641908, 2019). "In both murine and human breast cancer models, tumor progression was associated with the activation of inflammasome components and subsequent elevated levels of IL-1β at primary and metastatic sites." (PMID 31231372, 2019). "In a breast cancer model, mice deficient for caspase-1 and thereby having reduced IL-1β levels exhibited significantly lower numbers of lung metastasis and attenuated tumor growth." (PMID 30042333, 2018). "Interleukin-1B (IL-1B) is a pro-inflammatory cytokine whose expression in primary tumours has been identified as a potential biomarker for predicting breast cancer patients at increased risk for developing bone metastasis." (PMID 29760166, 2018). "GPER activation upregulates interleukin-1 receptor-1 (IL1R1) expression on breast cancer cells and interleukin (IL)-1β expression on cancer associated fibroblasts in a signalling loop to encourage invasive features of breast cancer." (PMID 29899833, 2018). "IL-1B has been linked with poor prognosis in breast cancer, whereas tumour-induced IL-1A has been linked to CCL22 production by tumour-infiltrating immune cells." (PMID 29760166, 2018). "Here, we provide a detailed overview of the molecular mechanisms underlying primary breast cancer development and formation of metastasis in bone, reporting recent evidence that suggest a pivotal role of IL-1B in these processes." (PMID 29760166, 2018). "Interleukin (IL)-1B is a pro-inflammatory cytokine whose expression in primary tumours has been identified as a potential biomarker for predicting breast cancer patients at increased risk for developing bone metastasis." (PMID 29760166, 2018). "IL-1β is linked to increased metastasis in various in vivo models and has been linked with bone-homing in breast cancer." (PMID 28551814, 2017). "To avoid the severely retarded growth effect caused by the double knockdown, we used IL-1β-neutralizing antibody to treat LCN2-depleted MDA-MB-231 breast cancer cells for evaluating the colony formation." (PMID 28281525, 2017). "Together, suggest that high local or systemic IL-1β plus CXCL1 plus CCL2 plus S100A8 plus VEGF plus IL8 in breast cancer patients represents a diagnostic biomarker for the existence of IRISOE TNBC tumor, and propensity to reduced RFS, DMFS, or OS." (PMID 29262555, 2017). "Our results show that tumor growth is associated with elevated levels of IL-1β in tumor microenvironments in mouse mammary tumor models and human breast cancer tissues." (PMID 28955343, 2017). "Data from patients with breast cancer suggest that IL-1β, IL-6, IL-8 and TNF-α contribute to chemotherapy-associated cognitive impairment." (PMID 28542626, 2017). "Within breast cancer, raised IL-1β levels are associated with poorly differentiated and more aggressive carcinomas." (PMID 28607534, 2017). "In this study, we demonstrated that inflammasome activation and IL-1β production in tumor-associated macrophages provided an inflammatory microenvironment promoting breast cancer progression." (PMID 27786298, 2016). "The IL-1β was the only cytokine in our study where higher levels were associated with increased risk of post-menopausal breast cancer." (PMID 27391324, 2016). "The ox-LDL and TNF-α variables showed inverse associations, while IL-1β was associated with increased breast cancer risk." (PMID 27391324, 2016). "We have recently identified IL-1B as a potential prognostic biomarker for early breast cancer patients at increased risk for the subsequent development of skeletal metastases." (PMID 27765923, 2016).